EGFR (epidermal growth factor receptor)
Diseases named in the same sentence as EGFR in open-access papers (continued):
Sharing a sentence is not in itself a finding about the gene and the disease.
oral cancer (continued). "In addition, activation of EGFR signalling is associated with tumor aggression events, such as metastasis and chemotherapy resistance, and is a poor prognostic biomarker in oral cancer." (PMID 26462152, 2015). "EGFR activation is known to be associated with the malignant phenotype, angiogenesis, inhibition of apoptosis as well as increased metastatic potential in oral cancer." (PMID 25918252, 2015). "In a study cohort of 145 patients with OPM lesions, a high EGFR expression was associated with increased oral cancer risk and reduced time to oral cancer, suggesting a promoting role of EGFR in oral malignant transformation and the prognostic implication of EGFR expression." (PMID 26462152, 2015). "Thus, the aim of the study was to investigate the functional role of Ley and the association of Ley with EGFR in oral cancer." (PMID 25799278, 2015). "In oral cancer, overexpression of EGFR has been associated with chemoresistance and poor prognosis." (PMID 24765152, 2014). "The results indicate that EGFR has an association with the aggressiveness of oral cancer." (PMID 12915878, 2003). "Likewise, one study suggests that EGFR inhibition slightly improves survival compared to conservative therapy, and another shows that ErbB mutations are extremely rare in oral oncogenesis (0.41% of oral cancer cases analysed have mutations)." (PMID 35954497, 2022). "Finally, our study of oral cancer patients suggests that β-catenin-mediated cross-talk between EGFR and Wnt signaling may underlie the effect of EGFR during tumor development." (PMID 20302655, 2010). "This study determined the association of EGFR, NFκB, COX-2, and miRNAs expression with the chewing habits and high-risk human papillomavirus (HR-HPV) infection in oral cancer patients." (PMID 41729911, 2026). "The EGFR gene is frequently overexpressed in oral cancer due to amplification, contributing to the activation of this pathway." (PMID 40723400, 2025). "EGFR-targeted therapies have proven particularly efficacious in HPV-related oral cancers, utilizing agents like cetuximab and erlotinib to obstruct EGFR signaling and impede tumor proliferation and metastasis." (PMID 40284275, 2025). "A high EUDAL/EGFR/STAT3/autophagy pathway activation predicts poor response to chemotherapy in oral cancer patients." (PMID 40940319, 2025). "In this study, we demonstrated that in oral cancer cells harboring wild-type (wt) EGFR, hypoxia can induce ligand-independent EGFR phosphorylation." (PMID 40940319, 2025). "Previous studies have shown that afatinib can target the EGFR/mTOR/Mcl-1 axis, inducing tumor cell apoptosis, and has the potential to become a treatment strategy for oral cancer." (PMID 40696350, 2025). "Intriguingly, we found that human oral cancer cells exhibit different EGFR phosphorylation responses to hypoxia." (PMID 40940319, 2025). "Afatinib, targeting the EGFR/mTOR/Mcl-1 axis, shows promise as a therapeutic strategy for oral cancer, especially in patients with high EGFR and Mcl-1 expressions." (PMID 38888847, 2025). "Knowledge of these hallmark features opens the door for targeted therapies, such as EGFR inhibitors, immune checkpoint blockers, and anti-angiogenic agents, to guide advances in oral cancer management." (PMID 40227635, 2025). "In conclusion, these findings highlight magnolol's ability to enhance the efficacy of RT in oral cancer by targeting the EGFR/NF‐κB axis, inducing apoptosis, and modulating immune responses, presenting a promising therapeutic strategy for OSCC." (PMID 40830825, 2025). "Next, we investigated mTOR and its related proteins to determine the link between EGFR and Mcl-1 signaling by afatinib in oral cancer cell lines." (PMID 38888847, 2025). "The analysis revealed a correlation between the expression of p-EGFR and Mcl-1 proteins in oral cancer cell lines, with the highest coexpression observed in the OSCC cell lines HSC-3, SAS, and Ca9.22." (PMID 38888847, 2025).
oral cancer (continued). "We then evaluated the cytotoxic effects of MPS-1, Aurora-B, and KSP inhibitors in combination with the EGFR inhibitor Cetuximab on oral cancer cells." (PMID 39594688, 2024). "This study investigates the impact of solanine on inflammation, proliferation, and angiogenesis inhibition in multidrug-resistant oral cancer KB-Chr-8-5 cells through inhibition of the EGFR/PI3K/Akt/NF-κB signaling pathway." (PMID 39124760, 2024). "Given that the SCC-25 cell line serves as a model of oral cancer and exhibits elevated protein expression levels of EGFR, MPS-1, Aurora-B, and KSP compared to SCC-09 cells, we selected SCC-25 cells for the subsequent experiments in this study." (PMID 39594688, 2024). "Further, in vitro studies have shown that EGFR is abundantly expressed on oral cancer cells and that cetuximab-mediated antibody-dependent cellular cytotoxicity (ADCC) is a crucial process associated with the therapeutic efficacy of cetuximab." (PMID 39011480, 2024). "Solanine effectively reduces proliferation and angiogenesis in multidrug-resistant oral cancer cells (KB-ChR-8-5) by modulating the EGFR/PI3K/Akt/NF-κB signaling pathway." (PMID 39124760, 2024). "In oral cancer cells, nicotine exposure enhanced EGFR phosphorylation via α7 nAChR, leading to the activation of the MEK/ERK and PI3K-AKT pathway, thus indicating nicotine exposure to promote oral cancer cell growth and migration." (PMID 39169426, 2024). "This study’s primary goal is to understand how solanine modulates the EGFR/PI3K/Akt/NF-κB signaling pathway in multidrug-resistant oral cancer cells (KB-ChR-8-5)." (PMID 39124760, 2024). "Intriguingly, these two compounds had been previously reported as EGFR-TK inhibitors for oral cancer therapy by our same research group." (PMID 38529190, 2024). "Cetuximab, a monoclonal antibody against epidermal growth factor receptor(EGFR), has an established role in oral cancer." (PMID 39600631, 2024). "The rationale for combining antimitotic inhibition with Cetuximab, an EGFR inhibitor, to enhance the death of oral cancer cells is based on the complementary roles these proteins play in cell proliferation and survival." (PMID 39594688, 2024). "Main combination therapies based on EGFR targeting used in clinical and preclinical trials for oral cancer treatment." (PMID 37376101, 2023). "The overexpression of the epidermal growth factor receptor (EGFR) correlates with the aggressive behavior of oral cancer." (PMID 37370896, 2023). "In this review, we explore current clinical and preclinical evidence that supports the potential use of EGFR inhibitors to address pain and morphine tolerance in oral cancer, in addition to their established role as effective anticancer agents." (PMID 38004424, 2023). "Our results suggest that immunohistochemical detection of EGFR should be routinely included in the prognostic evaluation of patients with oral cancer, using 10% of EGFR+ tumor cells as a cut-off point to consider a positive case." (PMID 37569265, 2023). "EGFR overexpression in oral cancer correlates with a malignant phenotype, suppression of apoptosis, and increased metastatic potential." (PMID 37370896, 2023). "In fact, EGFR expression in oral cancer is a powerful independent prognostic indicator for overall survival (OS), disease-free survival (DFS), and a reliable predictor of the likelihood of local–regional (LR) relapse." (PMID 37370896, 2023). "Previously, it has been shown that PXT prompts the death of squamous cells in human oral cancer cells by obstructing the EGFR signaling pathway." (PMID 37893061, 2023). "The scientists demonstrated that EGFR inhibitors, nimotuzumab and cetuximab, impeded the migration and invasion of oral cancer cell lines and human endothelial cells." (PMID 37513141, 2023).
oral cancer (continued). "In particular, we focused on the expression of specific markers of oral cancer, namely the epidermal growth factor receptor (EGFR) and steroid receptors such as the androgen receptor (AR) and the estrogen receptor (ER)." (PMID 37370896, 2023). "Our method directly examines the expression of oral cancer biomarkers, such as the epithelial growth factor receptor (EGFR), and steroid receptors, including the androgen receptor (AR) and the estrogen receptor (ER)." (PMID 37370896, 2023). "By inhibiting the EGFR/AKT pathway in oral cancer, quercetin appears to be an effective anti-tumor agent." (PMID 35529499, 2022). "They showed that FOXO1 played a critical role in suppressing cellular growth mediated by quercetin in oral cancer cells with high EGFR expression." (PMID 35462903, 2022). "It is demonstrated to have significant prognostic and clinicopathological significance in cancers, such as NSCLC, gallbladder cancer oral cancer.The epidermal growth factor receptor (EGFR) belongs to the ERBB family of tyrosine kinase receptors." (PMID 36401689, 2022). "The overexpression of Epidermal Growth Factor Receptor (EGFR) and dysregulation of its downstream effector pathways are important molecular hallmarks of oral cancers." (PMID 36008552, 2022). "Multiple studies have shown the use of Epidermal Growth Factor Receptor (EGFR)-targeted fluorescent tracers (e.g., panitumumab-800CW and cetuximab-800CW) to detect malignant LNs ex vivo in oral cancer patients using fluorescence molecular imaging." (PMID 35541024, 2022). "None study till date has reported effect of PBPs on expression of EGFR and its downstream effector pathway in experimental oral cancer." (PMID 36008552, 2022). "Lee and colleagues demonstrated that EGFR modulates the localization, stability, and transcriptional activity of β-catenin in oral cancers." (PMID 35744950, 2022). "Another study explored the mechanism of the epidermal growth factor receptor (EGFR)-targeting peptide to deliver siRNA into EGFR-overexpressing oral cancer cells, aiming the silencing of the target oncogene." (PMID 35402305, 2022). "For instance, fluorescently labeled EGFR antibodies have been found to be highly selective and specific in surgical margin delineation for oral cancers." (PMID 35884477, 2022). "Both oral cancer cell lines showed expression of E-cadherin, whereas EGFR expression was significantly higher in HSC-3 than in SAS cells." (PMID 35928727, 2022). "EGFR overexpression was increased in oral cancer and OSMF compared to healthy controls (p = 0.000; χ2 = 68.620)." (PMID 36010285, 2022). "Immunoexpression of EGFR was correlated with the survival rate of oral cancer patients, and the authors have concluded EGFR to be an independent prognostic factor for the assessment of survival rates." (PMID 36010285, 2022). "The ELDR is highly expressed in oral cancer samples compared to normal cells and induces cell proliferation by increasing EGFR and ILF3/cyclin E1 signaling." (PMID 35378133, 2022). "In this study, we administered apatinib in combination with anti-epidermal growth factor receptor (EGFR) targeted and systemic chemotherapy for the treatment of oral cancer and to achieve better disease outcomes." (PMID 34761117, 2021). "The ERbB1 gene, responsible for encoding the EGFR threshold, is in the short arm of chromosome 7p12 and has been found to show increased activity in oral cancer." (PMID 33810374, 2021). "Up-regulation of c-Met signaling is seen in oral cancer, which contributes to treatment resistance to epidermal growth factor receptor (EGFR)-targeting therapies." (PMID 34765739, 2021). "Previous studies have shown that EGFR is highly expressed in oral cancer and correlates with poor prognosis." (PMID 34298758, 2021).
oral cancer (continued). "In OPSCC and oral cancer, S100A8/S100A9 is often downregulated, associated with lower tumor grading, upregulation of apoptosis-related genes, decreased EGFR expression, epithelial differentiation and decreased migration and invasion." (PMID 33469045, 2021). "al. revealed that EGFR, which is a therapeutic target for oral cancer, was overexpressed in oral cancer cells." (PMID 33472170, 2021). "The epidermal growth factor receptor is the only available tyrosine kinase molecular target for treating oral cancer." (PMID 34283052, 2021). "Inhibition of EGFR with cetuximab attenuates nociceptive behaviors in a mouse model of oral cancer pain." (PMID 34054523, 2021). "The studies have highlighted the role of H-Ras mutations in treatment failure or development of resistance to EGFR tyrosine kinase inhibitors such as cetuximab and erlotinib in oral cancer patients." (PMID 35047986, 2020). "Available data showed that more than 80% oral cancer patients and oral cancer cell lines exhibit an overexpression of EGFR." (PMID 32188144, 2020). "Here, for the first time, it is shown that dysregulation of EGFR takes place by epigenetic mechanisms in oral cancer." (PMID 33317464, 2020). "There are other anti-EGFR antibodies under investigation for use in combination with chemo- and radio-therapy for oral cancer treatment such as zalutumumab, panitumumab and nimotuzumab." (PMID 35047986, 2020). "As expected, C-mab induced ADCC in oral cancer cells with expression of EGFR, thus showing the cell-killing effect." (PMID 32878053, 2020). "It has been reported, based on cell line studies, that overexpression of EGFR can impact on the development of solid tumors, including oral cancer." (PMID 33317464, 2020). "Higher levels of STAT3 and its effectors are proposed to intensify the metastatic potential of oral cancer, and increase its resistance to chemo-, radio- and EGFR-directed therapies." (PMID 35047986, 2020). "For example, the evaluation of Epidermal Growth Factor Receptor (EGFR) expression is highly necessary for therapeutic planning of anti-EGFR drugs in patients with lung or oral cancer." (PMID 31263455, 2019). "For example, in human oral cancer cells, it was shown that bacteria of interest were able to activate EGFR through the generation of hydrogen peroxide." (PMID 29924794, 2018). "The authors found that NAC suppresses growth of cancer cells by mediating the EGFR/Akt/HMG box-containing protein 1 signaling pathway in oral cancer cells, as well as tumor growth." (PMID 29849877, 2018). "In a previous study, we demonstrated that HBP1 is a downstream effector of the EGFR (epidermal growth factor receptor))/Akt pathway in oral cancer." (PMID 28099936, 2017). "We investigated the immunohistochemical utility of EMab-51 in human oral cancers because high EGFR expression was observed in oral cancer cell lines, such as HSC-2 and HSC-3." (PMID 28891752, 2017). "The rationale of choosing these CNA associated genes was basically due to LRP12, TPM2, EGFR, CCND1 being matched with ICGC and TCGA databases whereas FSCN1, CLPTM1L, CHL1 and CSMD1 had been found to be associated with oral cancer." (PMID 28384287, 2017). "EGFR protein expression was previously detected in various solid tumors, and EGFR expression correlated with cell migration/invasion in breast and oral cancer cell lines." (PMID 28881820, 2017). "Previously, we demonstrated that HBP1 functions as a downstream effector of the EGFR/Akt signaling pathway in oral cancer." (PMID 28099936, 2017). "In conclusion, of 156 clones of anti-EGFR mAbs, EMab-134 was highly efficacious in Western blot analysis and strongly stained oral cancers." (PMID 29090976, 2017). "Agents used in oral cancer preclinical and clinical chemoprevention studies include inhibitors of cyclooxygenase 2 (Cox-2) and epidermal growth factor receptor (EGFR)." (PMID 29109723, 2017).
oral cancer (continued). "We performed immunohistochemical analysis using EMab-134 for human oral cancers because EGFR expression was highly observed in oral cancer cell lines." (PMID 29090976, 2017). "In conclusion, of 100 clones of anti-EGFR mAbs, EMab-51 was highly efficacious in Western blot analyses and produced strong staining in oral cancers." (PMID 28891752, 2017). "In conclusion, CMP and its ingredient cordycepin can inhibit tumor growth and malignant transformation in a mouse model for oral cancer via inhibition of EGFR- and IL-17RA-signaling and enhancement of anti-tumor immunity." (PMID 29212184, 2017). "In a previous study, we demonstrated that quercetin is a potent anti-growthagent in EGFR-overexpressing oral cancer cells, where quercetin inhibits cell growthand induces apoptosis through modulation of the EGFR/Akt/FOXO1 axis." (PMID 27510965, 2016). "For oral cancer therapy, cetuximab, which targets the epidermal growth factor receptor (EGFR) is available for clinical use." (PMID 26927065, 2016). "Those included an mTOR inhibitor (AMPK agonist) and an EGFR inhibitor (gefitinib), two targets that have been previously reported to prevent oral cancer development in the 4-NQO model." (PMID 27027432, 2016). "LeY induces the activation of EGFR, and promotes the migration of oral cancer cells by the glycosylation of EGFR." (PMID 26636541, 2016). "In this study, the suppression of ERK phosphorylation was also seen, in line with the previous report of MEK-ERK induced downregulation of CXCL14 by activation of epidermal growth factor receptor (EGFR) in oral carcinoma cells." (PMID 26733763, 2016). "EGFR, an important mediator of EGFR signaling in oral cancer development, was also decreased by ER maleate." (PMID 26934445, 2016). "Since most oral cancers are epithelial in origin, there is a high probability of EGFR overexpression." (PMID 25918252, 2015). "In this study we investigate a targeted approach by treating oral cancer with an anti-EGFR monoclonal antibody in combination with photodynamic therapy (PDT)." (PMID 25918252, 2015). "Various studies have highlighted the role of EGFR in the pathogenesis of oral carcinoma, and this protein is also frequently expressed in many types of cancer, including HNSCC." (PMID 26179909, 2015). "Both immunofluorescence and western blotting results showed a substantial amount of EGFR expression in oral cancer cells." (PMID 25918252, 2015). "Epidermal growth factor receptor (EGFR) is highly expressed in oral cancer and is a target for cancer therapy and prevention." (PMID 25918252, 2015). "We demonstrated that EGFR inhibitors nimotuzumab and cetuximab exhibits anti-angiogenic properties by inhibiting the migration and invasion of oral cancer cell lines and human endothelial cells." (PMID 25918252, 2015). "Our results also provide insight into how Ley glycosylation manipulates EGFR signaling in oral cancer." (PMID 25799278, 2015). "Our results provide insight into how Ley glycosylation manipulates EGFR signaling in oral cancer and indicate that Ley is a potentially important biomarker and treatment target in Ley-overexpressing oral cancers." (PMID 25799278, 2015). "In conclusion, PDT outcome of oral cancer can be improved when combined with EGFR inhibitor nimotuzumab." (PMID 25918252, 2015). "In this present work, we evaluate the efficacy of photodynamic therapy (PDT) in combination with an EGFR inhibitor, nimotuzumab in oral cancer cell lines and OSCC xenograft tumor model." (PMID 25918252, 2015).